MIR187 (microRNA 187)
Synonyms: hsa-mir-187; MIRN187; miR-187; miRNA187
Gene: MicroRNA gene on chromosome 18 (35,904,818 to 35,904,926, reverse strand). Ensembl gene ENSG00000207797.
Gene Ontology:
Biological process: miRNA-mediated post-transcriptional gene silencing
Cellular component: RISC complex
Homologues: Orthologues: chimpanzee MIR187 (98% identical), macaque mml-mir-187 (97% identical), dog MIR187 (61% identical), rabbit MIR187 (61% identical), zebrafish mir187 (58% identical), mouse Mir187 (55% identical), tropical clawed frog xtr-mir-187 (55% identical), guinea pig MIR187 (51% identical).